UBE2S (ubiquitin conjugating enzyme E2 S)
Diseases named in the same sentence as UBE2S in open-access papers (continued):
Sharing a sentence is not in itself a finding about the gene and the disease.
cancer (continued). "Numerous studies have demonstrated that the occurrence and development of diverse types of malignant tumors could be affected by UBE2S." (PMID 38312603, 2024). "What is the prognostic value of the UBE2S gene in patients with pan-cancer?" (PMID 38312603, 2024). "Moreover, using the HPA database, we found that UBE2S depicted strong staining in the 12 OC tissues, which further confirmed its abnormally high protein expression in cancer tissues." (PMID 38115063, 2023). "In summary, few studies have described the immune-oncology pattern of UBE2S in human cancers." (PMID 35578600, 2022). "UBE2S exhibited abnormally high expression at the pan-cancer level." (PMID 35658829, 2022). "Furthermore, gene expression analysis on 18 types of human tumor tissues and matching adjacent normal tissues revealed that UBE2S expressed higher in 15 types of cancer tissues based on the TCGA database." (PMID 35658829, 2022). "First, the expression level of UBE2S was analyzed at a pan-cancer level." (PMID 35658829, 2022). "All these findings may provide novel insights into the essential immune-oncology properties of UBE2S in the field of cancer research." (PMID 35578600, 2022). "Compared with normal or para-carcinoma tissues, UBE2S expression was found to be distinctly higher in a series of cancers, suggesting that UBE2S may play an oncogenic role across these cancers." (PMID 35578600, 2022). "Studies have shown that UBE2S is highly expressed in many cancers." (PMID 34123793, 2021). "Currently, UBE2S upregulation is important in the prognosis of many human cancers." (PMID 34535173, 2021). "One possibility is that Ube2S may function as the predominant chain-extending enzyme in normal cells, but that Ube2K can acquire that role when it is overexpressed in cancer cells." (PMID 34586382, 2021). "Some studies show that Ube2S is overexpressed in human malignancies and may contribute to cancer development." (PMID 32038111, 2020). "However, whether UBE2S can be used as a biomarker for cancer detection and a therapeutic target remains to be investigated, for example, as a diagnostic biomarker for pan-cancer?" (PMID 38312603, 2024). "Notably, a higher UBE2S expression indicated a higher level of stemness, TMB, MSI, and MMR deficiency and DNA methyltransferases, as well as chemotherapeutic resistance in various cancers." (PMID 35578600, 2022). "The outcomes of the IHC staining exhibited that the pattern of UBE2S expression was evident, namely, in the cytoplasm and nucleus, HIF‐1α and FOXM1 expression were major situated in the cancer cells nucleus." (PMID 41427004, 2025). "Dysregulation of UBE2S can lead to the accumulation of β-catenin, activating WNT target genes and promoting tumorigenesis in cancers such as CRC." (PMID 39851497, 2025). "Kruskal–Wallis test was employed to compare the protein expression differences of UBE2S, HIF‐1α, and FOXM1 in the adjacent tissues, HIN, LIN, and cancer tissues." (PMID 41427004, 2025). "Studies have reported that UBE2S targets VHL for degradation to regulate tumor growth and metastasis in various cancers." (PMID 37563971, 2023). "Further investigation of BIRC5, H2AFZ, HIST1H2BK, KIF15, UBE2S, and FBXO5 is crucial to broaden the understanding of cancer invasion and migration, and to promote the discovery and evaluation of new therapeutic targets." (PMID 35406376, 2022).
cancer (continued). "The expression levels of UBE2S, PTTG1, and CDC20 were significantly higher in most cancer tissues than in normal tissues." (PMID 34726341, 2021). "Furthermore, our investigation revealed that UBE2S, HIF‐1α, and FOXM1 exhibited significant upregulation in both esophageal intraepithelial neoplasia and cancer, with statistically significant variations observed." (PMID 41427004, 2025). "The positive regulatory relationship between UBE2S and hypoxia-inducible factor 1α (HIF-1α) in cancer cells might contribute to greater proliferation, angiogenesis, and metastasis of cancer." (PMID 33810518, 2021). "Ubiquitin-conjugating enzyme E2S (UBE2S), a potential oncogene related to the PI3K/AKT/mTOR pathway, could be involved in apoptosis, proliferation, and migration, and it is valuable as a biomarker in the prognosis of cancer." (PMID 40804837, 2025). "UBE2S, HIF‐1α, and FOXM1 may play a role in the progression of esophageal HIN and LIN to cancer." (PMID 41427004, 2025). "In addition, in cancer tissues, UBE2S exhibited abnormally high expression not only at the mRNA level but also at the protein level." (PMID 38115063, 2023). "In addition, UBE2S promoted cell chemoresistance through PTEN-AKT signaling in HCC, which indicated that UBE2S may be a novel oncogene in the development of cancer." (PMID 36250027, 2022).
tumor (39 papers, 2008 to 2026). "To determine the role of the STAT3/UBE2S/NKp30 axis in vivo, we established a PC-9 subcutaneous tumor model using C-NKG mice deficient in T cells, B cells, and NK cells." (PMID 41254082, 2025). "UBE2S, a ubiquitin-conjugating enzyme, regulates cell cycle progression, apoptosis, and protein ubiquitination, which are directly associated with tumor growth." (PMID 38577593, 2024). "For example, the high-risk genes EMC6 and UBE2S were expressed to a greater extent in TCGA-PRAD tumor tissues than in normal tissues." (PMID 37007952, 2023). "Taken together, UBE2S is associated with various cancerous phenotypes, including tumor proliferation, migration, prognosis, immune infiltration and evasion, and therapy response, which supports UBE2S as an immune-oncogenic molecule." (PMID 35578600, 2022). "External experimental validation was conducted to delineate the association of UBE2S with tumor phenotypes through assays of proliferation, colony formation, and migration." (PMID 35578600, 2022). "In a total of 845 HCC patients, the elevated expression of UBE2S was significantly associated with higher tumor grade, larger tumor volume, vascular invasion, higher serum AFP level, advanced TNM stage, recurrence, and poorer outcomes." (PMID 36262473, 2022). "In summary, these findings show that high UBE2S expression and active Akt1 are associated with adverse tumor characteristics." (PMID 34123793, 2021). "In summary, the findings of this study show that higher levels of UBE2S are associated with a greater tumor burden, poor response to neoadjuvant therapy, and worse overall survival for LGG patients." (PMID 34123793, 2021). "Notably, UBE2S has been found to bind and degrade p63 via K16-linked ubiquitination, thereby promoting the G1/S transition in PCa tumor cells both in vivo and in vitro." (PMID 38312603, 2024). "However, there is little knowledge about the pathogenic role of UBE2S in the immune-oncology context of the tumor microenvironment (TME), mutation burden, prognosis, and therapeutic response across different tumors." (PMID 35578600, 2022). "Therefore, UBE2S is frequently regarded as an oncogenic factor and is intimately linked to resistance to tumor therapy, and the targeting of UBE2S may represent a promising therapeutic approach." (PMID 38312603, 2024). "The investigation found a significant relationship between elevated levels of UBE2S and ethnicity (p < 0.001) in addition to the tumor site (p = 0.021)." (PMID 41427004, 2025). "Preliminary single-cell RNA sequencing (scRNA-Seq) analysis of tumor-infiltrating natural killer (TiNK) cells derived from NSCLC patients indicated a significant upregulation of the ubiquitin-conjugating enzyme E2S (UBE2S)." (PMID 41254082, 2025). "Critically, we identified UBE2S, a ubiquitin-conjugating enzyme upregulated in tumor-infiltrating NK (TiNK) cells from NSCLC patients and our in vitro models, as a likely mediator of this process." (PMID 41254082, 2025). "Our current results showed that UBE2S overexpression was related to the tumor location, however, with only nine samples in the upper position, we need to expand the sample size to further verify." (PMID 41427004, 2025). "Hypoxia‐inducible factor (HIF)‐1α is regulated by the ubiquitin‐conjugating enzyme E2S (UBE2S) to enhance the growth, invasion, and metastasis of the tumor in ESCC." (PMID 41427004, 2025). "Collectively, these findings underscore the potential of targeting the STAT3/UBE2S/NKp30 axis as a viable approach to impede NSCLC tumor growth and improve clinical outcomes." (PMID 41254082, 2025).
tumor (continued). "The ubiquitin-conjugating enzyme E2S (UBE2S), a member of the ubiquitin-binding enzyme family, is associated with tumor size, stage, and TNM classification." (PMID 39388011, 2024). "First, in the four OC-GEO datasets (GSE38666, GSE40595, GSE18521, and GSE26712), UBE2S was found to be highly expressed in tumor tissues as compared to the normal ovarian tissues." (PMID 38115063, 2023). "Previous studies have shown that UBE2S can regulate tumor development through the VHL/HIF‐1α signaling pathway." (PMID 37563971, 2023). "Compared with normal tissues, IGFBP7, LBH and TFPI are low expressed in tumor tissues (P < 0.05), while KRT18, UBE2C and UBE2S were highly expressed in tumor tissues (P < 0.05)." (PMID 38077434, 2023). "The results showed that the high‐expression group had higher clinical stages (p = 0.021) and larger tumor size (p = 0.032), compared with the low UBE2S expression group." (PMID 37563971, 2023). "We also determined the ratio of lung metastatic nodule number per tumor weight for each mouse, and there were still significant differences between the two groups, which indicated that UBE2S knockdown reduced metastasis independently of tumor growth." (PMID 37563971, 2023). "The protein levels of UBE2S were higher in HCC tumor tissues than that in peritumoral liver tissues." (PMID 37563971, 2023). "Overexpression of UBE2S promotes tumor cell proliferation and migration by regulating the VHL/HIF-1α/STAT3 signaling pathway." (PMID 38115063, 2023). "The results indicated that upregulation of UBE2S mRNA, log2 (the concentration of UBE2S mRNA in tumor tissue/that in matched peritumoral tissue) > 1, was detected in 29 of 42 (69%) HCCs." (PMID 37563971, 2023). "Spearman correlation analysis showed that there was a positive correlation between the UBE2S and Ki‐67 mRNA expression levels, which was used as a proliferation marker for human tumor cells." (PMID 37563971, 2023). "Hereafter, we further characterized the alteration of predominant cellular composition, finding that UBE2S had an extensive and complex regulatory relationship with surrounding tumor cells." (PMID 35578600, 2022). "UBE2S has been reported to be overexpressed in tumors of the gastrointestinal system, urinary system, nervous system, and female reproductive system." (PMID 35658829, 2022). "Ubiquitin conjugating enzyme E2S (UBE2S), a member of the ubiquitin-conjugating enzyme family, is known to play a pivotal role in tumorigenesis and progression in some tumor types." (PMID 35578600, 2022). "The different expression levels of UBE2S and Ki-67 in tumor tissues were examined by immunohistochemical staining." (PMID 33589597, 2021). "We investigated the role of UBE2S in HCC and found UBE2S upregulation is relevant with large tumor size, recurrence, and advanced TNM stage, serving as an independent risk factor of overall survival (OS) and disease-free survival (DFS) for HCC patients." (PMID 34785642, 2021). "UBE2S silencing significantly reduced tumor volume and weight, whereas UBE2S overexpression promoted tumorigenesis in xenograft mice." (PMID 33589597, 2021). "To identify inhibitors of UBE2S that can attenuate tumor progression, we developed a luciferase-based high-throughput screen of small molecule compounds." (PMID 33589597, 2021). "The tumor tissue volumes of each group showed that, as same as in vitro, UBE2S induced Olaparib resistance through Wnt/β-catenin signaling pathway in vivo." (PMID 34535173, 2021). "The crucial roles of UBE2S in cell proliferation, cell differentiation, and DNA repair inevitably implicate its involvement in tumor progression." (PMID 34785642, 2021).
tumor (continued). "Analysis showed that UBE2S expression level was significantly up-regulated with increase in tumor grade in both TCGA and CGGA data set." (PMID 34123793, 2021). "UBE2S overexpression was related to ethnicity (p < 0.001) and the place of the tumor (p = 0.021)." (PMID 41427004, 2025). "Moreover, a positive correlation has been established between high UBE2S expression and advanced tumor stage, as well as poor patient prognosis." (PMID 38312603, 2024). "Despite the role of UBE2S in tumor proliferation, chemoresistance, and metastases, the function of accumulated UBE2S in epithelial OC and its association with platinum resistance remain largely unknown." (PMID 38115063, 2023). "Our study was similar to Pan's report and strongly indicated that UBE2S is a tumor oncogene in HCC and may be a novel potential therapeutic marker for HCC." (PMID 37563971, 2023). "In subcutaneous xenograft tumor models, the p21 protein levels in the UBE2S knockdown group (UBE2S‐shRNA) were significantly increased compared with those in the control‐shRNA group, while there were fewer Ki67‐positive cells in the UBE2S knockdown group than in the control‐shRNA group." (PMID 37563971, 2023). "The tumor sizes and weights of the UBE2S overexpression group were markedly increased." (PMID 37563971, 2023). "In addition, H&E staining of lungs confirmed that downregulation of UBE2S in HCC decreased the number of pulmonary metastatic nodules in liver orthotopic xenograft tumor models." (PMID 37563971, 2023). "Furthermore, it has been suggested that UBE2S-mediated ubiquitination of β-linked proteins may contribute to tumorigenesis and the progression of PCa bone metastases by facilitating alterations in key signaling pathways that promote tumor cell survival and proliferation." (PMID 37730847, 2023). "Presumably, EMC6 and UBE2S are overexpressed in tumor tissues compared with normal tissues." (PMID 37007952, 2023). "The results showed that downregulation of UBE2S significantly inhibited tumor size." (PMID 37563971, 2023). "Moreover, we randomly selected eight pairs of tumors to detect the protein level of UBE2S in tumor tissues, measured by western blotting." (PMID 37563971, 2023). "In addition, inhibition of UBE2S in combination with sorafenib synergistically decreased tumor growth in vivo." (PMID 37563971, 2023). "The correlation between the elevated UBE2S expression and the worse tumor phenotypes suggests that UBE2S may help tumor cells escape immune clearance through the interplay of immune cells with tumor cells." (PMID 35578600, 2022). "Besides, the expression of cell exhaustion-related genes, including PDCD1, CTLA4, LAG3, and TIGIT, was upregulated in several tumors, indicating that UBE2S was intensely involved in tumor evasion via different mechanisms." (PMID 35578600, 2022). "UBE2S also positively correlated with tumor number, tumor size, and tumor-node metastasis stage." (PMID 33589597, 2021). "In addition, immunohistochemical assays showed that the expression of UBE2S in the tumor tissues of the treatment group was significantly lower than that of the control group, whereas the expression of p27 was significantly increased." (PMID 33589597, 2021). "Furthermore, nuclear UBE2S also positively correlated with tumor number (P = 0.037) and tumor size (P = 0.003)." (PMID 33589597, 2021). "Immunostaining was used to detect the expression of Ube2S in normal and tumor tissues." (PMID 32038111, 2020). "Additionally, the role of UBE2S in conferring resistance to tumor treatment is examined." (PMID 38312603, 2024). "In addition, in liver orthotopic xenograft tumor models, the results were consistent with those of subcutaneous xenograft tumor models, which indicated that knockdown of UBE2S could inhibit tumor growth in vivo." (PMID 37563971, 2023). "Moreover, upregulation of UBE2S significantly improved tumor size." (PMID 37563971, 2023).